RB1 (RB transcriptional corepressor 1)
Diseases named in the same sentence as RB1 in open-access papers (continued):
Sharing a sentence is not in itself a finding about the gene and the disease.
adenosarcoma (1 paper, 2017). A low grade malignant neoplasm characterized by the presence of a benign epithelial component (tubular and cleft-like glands) and a low grade sarcomatous component that contains varying amounts of fibrous and smooth muscle tissues.
age-related macular degeneration (1 paper, 2011). Age-related loss of vision in the central portion of the retina (macula), secondary to retinal degeneration. "Our finding that Rb1 inhibits the release of VEGF from RPE cells suggests that Rb1 has a significant role in the eye to protect against angiogenic diseases such as age-related macular degeneration." (PMID 24527228, 2011).
amyotrophic lateral sclerosis (1 paper, 2022). Amyotrophic lateral sclerosis (ALS) is a neurodegenerative disease characterized by progressive muscular paralysis reflecting degeneration of motor neurons in the primary motor cortex, corticospinal tracts, brainstem and spinal cord. "For example, many SOD1 mutations can cause amyotrophic lateral sclerosis (ALS), NF1 mutations can cause pediatric brain tumors, RB1 mutations can cause retinoblastoma, and ETV6 mutations can cause pediatric acute lymphoblastic leukemia." (PMID 36276986, 2022).
aneuploidy (1 paper, 2013). Chromosomal disorder consisting of the presence a chromosomal abnormality in which there is an addition or loss of chromosomes within a set. "It is also possible that effects of RB1 inactivation on CIN and aneuploidy is cell-type specific and that human retinal cells lacking RB1 that have aneuploidy or CIN die during tumorigenesis but murine cells are more tolerant of such chromosomal defects." (PMID 23765217, 2013).
aortic valve disease (1 paper, 2018). "Intriguingly, two members of a human family carrying a retinoblastoma gene mutation have been found to have a bicuspid aortic valve potentially strengthening the importance of RB1 in aortic valve disease." (PMID 29304157, 2018). "Alternative Cre drivers, such as Periostin or Nfatc1, that target VICs at different developmental time points, including cells not derived from the Tie2 lineage, may further clarify the contributions of RB1 to aortic valve disease." (PMID 29304157, 2018).
Arrhythmia (1 paper, 2019). Any cardiac rhythm other than the normal sinus rhythm. "Therefore, Rb1 reduces [Ca2+]i overload caused by H-R and inhibits arrhythmias, as [Ca2+]i overload is an important factor in inducing arrhythmia." (PMID 31892729, 2019). "This study investigated the effects of Rb1 on INa, ICaL, potassium current and APs, and explored its potential pharmacological effects of Rb1 against arrhythmia and cardiac cell calcium overload." (PMID 31892729, 2019).
astrocytic tumor (1 paper, 2015). A glial tumor of the brain or spinal cord showing astrocytic differentiation. "Therefore, the present study aimed to evaluate the expression and methylation profiles of the genes CDKN2A, CDKN2B, CDC6, Bmi-1, CCND1, and RB1 in astrocytic tumors in the northern region of Brazil." (PMID 26317630, 2015).
benign retinal tumor (1 paper, 2020). "Retinocytoma is a rare benign retinal tumor associated with variants in the RB1 gene." (PMID 31997559, 2020).
benign smooth muscle tumors (1 paper, 2025).
bone osteosarcoma (1 paper, 2023). A usually aggressive malignant bone-forming mesenchymal neoplasm arising from the bone.
Branchioma (1 paper, 2023). A tumor derived from branchial epithelium or branchial rests. "Moreover, our case adds to the morphological (prominent neuroendocrine-like nested/organoid features) and immunophenotypic (CD34 expression combined with RB1 loss) heterogeneity/pitfalls related to the differential diagnosis of branchioma." (PMID 37401932, 2023). "In summary, we reported an unusual case of branchioma with neuroendocrine-like morphology lacking nuclear RB1 expression and harboring several pathogenic mutations." (PMID 37401932, 2023).
Cachexia (1 paper, 2020). Severe weight loss, wasting of muscle, loss of appetite, and general debility related to a chronic disease. "GE5, GE50 and Rb1 all reduced the liver weights of mice with cachexia (P < 0.01)." (PMID 32020864, 2020). "We found that GE5, GE50 and Rb1 can reduce the inflammatory cytokines TNF-α and IL-6 in cancer cachexia mice." (PMID 32020864, 2020).
cardiac tumors (1 paper, 2024). "A stop loss mutation in Rb1 and a translation start site mutation in Pdgfra were the most deleterious type detected in two separate cardiac tumors." (PMID 38232086, 2024).
choriocarcinoma (1 paper, 2010). An aggressive malignant tumor arising from trophoblastic cells. "Studies also revealed a different pattern of LOH in different histological types of nonseminomas for markers located within the genomic region containing the RB1 gene (13q14), varying from 0% in yolk sac tumor component to 50% in choriocarcinoma." (PMID 22933911, 2010).
cystic fibrosis (1 paper, 2021). Autosomal recessive disorder caused by pathogenic variants in the CFTR gene (cystic fibrosis transmembrane conductance regulator), which encodes a chloride and bicarbonate channel expressed in epithelial cells, and follow the diagnosis criteria. "Classification of genetic variants based on the effect on proteins does not exist for RB1 variants but has been described for other genetic diseases, i.e., cystic fibrosis." (PMID 33807189, 2021).
diffuse astrocytoma (1 paper, 2020). A low-grade (WHO grade II) astrocytic neoplasm. "Attempts to molecularly define the aggressive type of diffuse astrocytomas have suggested several genetic markers such as RB1 pathway alterations (e.g., CDKN2A/B homozygous deletion or CDK4 amplification), PIK3R1 mutation, PDGFRA amplification, or G-CIMP low type in the methylation cluster." (PMID 33228806, 2020).
DNA repair deficiency (1 paper, 2022).
Dyskinesia (1 paper, 2019). A movement disorder which consists of effects including diminished voluntary movements and the presence of involuntary movements. "In our previous study, we have proved that Rb1 can improve movement dysfunction and dopaminergic neuron death in MPTP mice, and here we used a gait dynamics test to further confirm the effect of Rb1 on the dyskinesia observed in the MPTP-treated mice." (PMID 31314744, 2019).
embryonal rhabdomyosarcoma (1 paper, 2013). A poorly circumscribed morphologic variant of rhabdomyosarcoma. "Whereas Pax3:Foxo1a expression was unaltered, biomarkers of aRMS versus embryonal rhabdomyosarcoma were both increased, questioning whether these diagnostic markers are reliable in the context of Rb1 loss." (PMID 24274149, 2013). "Genome-wide gene expression in Pax3:Foxo1a,Rb1 tumors more closely approximated aRMS than embryonal rhabdomyosarcoma." (PMID 24274149, 2013).
endometrioid tumor (1 paper, 2012). A benign, borderline, or malignant epithelial tumor of the female reproductive system characterized by the presence of glands and/or cysts lined by neoplastic cells that resemble endometrial cells.
energy metabolism disorder (1 paper, 2017). "In summary, Rb1 was able to target and inactivate RhoA and downstream signaling, which likely mediated the protective role of Rb1 in I/R-induced energy metabolism disorder and cardiomyocyte apoptosis, providing an explanation for the restoration of heart structure and function by Rb1 after I/R." (PMID 28327605, 2017). "Supporting this speculation, the present study demonstrated that Rb1 prevented I/R-enhanced expression of RhoA and activation of its downstream signaling, including ROCK1, MYPT and MLC, concurrently attenuating energy metabolism disorder and myocardium impairment." (PMID 28327605, 2017).
extragonadal germ cell tumor (1 paper, 2024). A germ cell tumor arising in an anatomic site other than the testis or ovary (e.g., central nervous system, lung, mediastinum, and retroperitoneum). "Mutations in the CCND2 and RB1 genes have been associated with the development of extragonadal germ cell tumors (EGCTs) found in the mediastinum." (PMID 39045558, 2024).
fibrosis (1 paper, 2020). the formation of excess fibrous connective tissue in an organ or tissue in a reparative or reactive process. "Interestingly, these downregulated miRNAs are also known to increase the expression of target genes HDAC1, HDAC2, and RB1 which increase global chromatin accessibility, increase cardiac fibrosis and decrease cardiac function." (PMID 33175850, 2020).
Globozoospermia (1 paper, 2015). Any structural anomaly of the acrosome resulting in a round sperm head. "Six imprinted genes showed different 5hmC patterns between normal and abnormal sperm (GDAP1L1, GNAS, KCNK9, LIN28B, RB1, RTL1), and five imprinted genes showed different 5hmC patterns between normal and globozoospermia sperm (KCNK9, LIN28B, RB1, SLC22A18, ZDBF2)." (PMID 25762640, 2015).
goblet cell adenocarcinoma (1 paper, 2023). "In appendiceal cancers, RB1 gene mutations are reported in some isolated cases of appendiceal cancers without further specification, low-grade appendiceal mucinous neoplasms, mucinous adenocarcinomas of the appendix, and appendiceal goblet cell adenocarcinoma, without being defined for them." (PMID 37509254, 2023).
histiocytic sarcoma (1 paper, 2015). An aggressive malignant neoplasm with a poor response to therapy, usually presenting as stage III/IV disease. "Highly recurrent loss of RB1 was also found in canine histiocytic sarcomas." (PMID 25955013, 2015).
hydatidiform mole (1 paper, 2023). A gestational trophoblastic disorder characterized by marked enlargement of the chorionic villi, hyperplasia of the villous trophoblastic cells and hydropic changes. "TSSC3 and RB1 could be used as an adjunct in the diagnosis of hydatidiform moles, particularly when p57 immunohistochemistry provides an equivocal result." (PMID 37298606, 2023).
Hyponatremia (1 paper, 2021). An abnormally decreased sodium concentration in the blood.
insomnia (1 paper, 2021). A sleep disorder characterized by difficulty in falling asleep and/or remaining asleep. "Klf8 was inactivated in antidepressant and insomnia treatments (sertraline, fluoxetine, suvorexant, imipramine, and 8beta) and strongly activated in neurotoxic conditions (Domo, Pb, and rb1 mutants)." (PMID 34211495, 2021).
iron deficiency (1 paper, 2025). "Iron deficiency impairs skeletal muscle regeneration by stabilizing HIF‐2α in MuSC, inducing Rb1 RNA expression, and repressing E2F‐dependent proliferation." (PMID 41292279, 2025).
ischemic stroke (1 paper, 2019). A stroke disorder caused by obstruction of blood flow to the brain, due to thrombotic (local blood clot formation) or embolic (due to a blood clot or other material traveling from another site) event. "Ginsenoside Rg1 and ginsenoside Rb1 increased GLUT3 expression and ATP yield in mice after ischemic stroke, and Rb1 transportation across blood–brain barrier (BBB) was partly regulated by GLUT1 on microvascular endothelial cells." (PMID 31065240, 2019).
keloid (1 paper, 2022). An irregularly shaped, elevated mark on the skin caused by deposits of excessive amounts of collagen during wound healing. "Since the downstream genes of RB1 are related with M2 macrophages, for example: C1QC,C1QB,MRC1, fibroblasts in keloid may be beneficial for the transition and proliferation of M2 macrophages." (PMID 35990663, 2022).
kidney damage (1 paper, 2025). "In summary, our study suggests that Rb1 can target VEGFR2, activate the AKT signalling pathway, and ultimately reduce kidney damage." (PMID 40682486, 2025).
leiomyomatosis (1 paper, 2022). A condition characterized by the presence of numerous small benign smooth muscle neoplasms located throughout the body.
lipomatosis (1 paper, 2023). A neoplastic process characterized by diffuse overgrowth of mature adipose tissue. "Such conditions are often linked to germline alterations in retinoblastoma 1 (Rb1), leading to generalized lipomatosis." (PMID 37521590, 2023).
Lobular Carcinoma (1 paper, 2022). "However, more studies are required to better understand the role of Cyclin D1 and Rb1 in lobular carcinoma before drawing any conclusions." (PMID 35743985, 2022).
lung adenoma (1 paper, 2016). A benign, well circumscribed epithelial neoplasm that arises from the bronchus or the lung parenchyma.
macrosomia (1 paper, 2015). "The suppression of RB1 may partly cause the excessive trophoblast proliferation in macrosomia." (PMID 26598317, 2015). "Expression levels of SMAD4, SMAD3, RB1 and EP300 genes were significantly decreased in placentas of neonates with macrosomia compared with those of controls." (PMID 26598317, 2015).
migraine (1 paper, 2019). "Ev, Rb1, and 6-Gi showed positive correlations with NO-p and NO-b, which were also observed in another migraine mice model induced by reserpine, indicating that the effect of Ev, Rb1, and 6-Gi on NO was stable." (PMID 30915149, 2019). "The positive correlations with 5-HT and 5-HIAA of Ev, Rb1, and 6-Gi were also observed in another migraine mouse model induced by reserpine, indicating that increasing 5-HT and promoting its metabolism may be the main role of these ingredients with max concentrations." (PMID 30915149, 2019).
mismatch repair deficiency (1 paper, 2024).
Myocardial fibrosis (1 paper, 2026). "This study will open up a new insight into the relationship between Rb1 and miRNA-21, which mitigates myocardial fibrosis in the Ang II-induced mouse model." (PMID 41885708, 2026).
myoepithelial carcinoma (1 paper, 2017). "In summary, we report a case of myoepithelial carcinoma with a RB1 inactivating mutation that experienced a dramatic response to platinum-based chemotherapy." (PMID 28390395, 2017). "RB1 pathway deregulation has been reported in various benign and malignant salivary tumors, including malignant myoepithelioma." (PMID 28390395, 2017).
myosarcoma (1 paper, 2019). "As the interaction network of upregulated and downregulated miRNAs displays, we found that FOS, TGFB1, RB1 and ID2 are important genes controlling proliferation and apoptosis in myosarcoma." (PMID 30717351, 2019).
oligodendroglial tumor (1 paper, 2016). Oligodendrogliomas are cerebral tumors that are differentiated from other gliomas on the basis of their unique genetic characteristics and better response to chemotherapy. "Regarding the gene alterations among specific types of tumors, high incidence of loss of chromosome 1p and 19q and methylation of several genes, such as MGMT, estrogen receptor gene, RB1, TP73, TP14, TP15, and TP16, have been found to be characteristics of oligodendroglial tumors." (PMID 27367901, 2016).
opisthorchiasis (1 paper, 2015). Infection with flukes of the genus Opisthorchis. "One study also demonstrated alterations of RB pathway related genes such as RB1, p16INK4, cyclin D1, and CDK4 in hamster CCA model of opisthorchiasis." (PMID 26313366, 2015).
oropharyngeal tumors (1 paper, 2013).
osteoblastic osteosarcoma (1 paper, 2017). A conventional osteosarcoma characterized by the predominance of osteoid matrix.
osteoma (1 paper, 2023). A benign, well-circumscribed, bone-forming neoplasm predominantly composed of lamellar bone.
osteoporosis (1 paper, 2025). A condition of reduced bone mass, with decreased cortical thickness and a decrease in the number and size of the trabeculae of cancellous bone (but normal chemical composition), resulting in increased fracture incidence. "Another study demonstrated the anti-osteoporosis activity of Rb1 in dexamethasone (DEX)-induced osteoporosis rat model by regulating aryl hydrocarbon receptor (AHR)/proline/arginine-rich end leucine-rich repeat protein (PRELP)/NF-κB signaling pathway." (PMID 40507179, 2025).
ovarian epithelial tumor (1 paper, 2015). A benign, borderline, or malignant tumor that originates from the surface epithelium of the ovary. "This study aimed to determine the frequency of expression of Rb1, P16 and ER in ovarian epithelial tumors by immunohistochemistry." (PMID 26043844, 2015). "The specific aim of this study is to determine the frequency of expression of ER, Rb1 and P16 by immunohistochemistry (IHC) in tissue sections prepared from formalin fixed, paraffin embedded tissue blocks of ovarian epithelial tumors." (PMID 26043844, 2015). "We studied Rb1, P16 and ER protein expression in a relatively large cohort of ovarian epithelial tumors of varying histotypes and grades to evaluate the frequency and patterns of expression and correlate with clinico-pathologic parameters." (PMID 26043844, 2015).
parasitic diseases (1 paper, 2024). "Through the prediction of OTU function, the results showed that the risk of parasitic diseases in aging mice was further reduced when Rb1 and Re were simultaneously interfered, and there was a significant difference between the aging group and the control group." (PMID 39346650, 2024).
parotid tumors (1 paper, 2024). "We show in an adult patient with de novo germline RB who exhibited extraocular parotid tumors in adulthood that our approach revealed that the germline variant in RB1 in this participant arose from the paternal allele." (PMID 39724000, 2024).